ZBTB11 (zinc finger and BTB domain containing 11)
Description:
May be involved in transcriptional regulation.
Synonyms: ZNF-U69274; ZNF913; MRT69
Tractability: PROTAC: UniProt records ubiquitination sites on it; ubiquitination databases record sites on it; its protein half-life has been measured.
Target class: Transcription factor
Gene: Protein-coding gene on chromosome 3 (101,648,889 to 101,677,135, reverse strand). Ensembl gene ENSG00000066422.
Subcellular location: Nucleus, nucleolus
Subcellular location (Human Protein Atlas): Nucleoplasm
Gene Ontology:
Molecular function: DNA-binding transcription factor activity, RNA polymerase II-specific; RNA polymerase II cis-regulatory region sequence-specific DNA binding
Biological process: regulation of DNA-templated transcription; regulation of transcription by RNA polymerase II
Cellular component: nucleoplasm; nucleus; nucleolus
Genetic constraint (gnomAD): Loss-of-function variants: 66 observed, 108.57 expected, observed/expected ratio (o/e) 0.61, 90% interval 0.5 to 0.75. The upper end of that interval is the gene's LOEUF score, 0.75, which puts it in group 3 of 6, group 1 being the genes least tolerant of losing a copy. Missense variants: 1,100 observed, 1,309.9 expected, observed/expected ratio (o/e) 0.84, 90% interval 0.8 to 0.88. Synonymous variants: 516 observed, 468.74 expected, observed/expected ratio (o/e) 1.1, 90% interval 1.02 to 1.18.
Homologues: Orthologues: chimpanzee ZBTB11 (99% identical), macaque ZBTB11 (98% identical), rabbit ZBTB11 (93% identical), dog ZBTB11 (93% identical), pig ZBTB11 (92% identical), guinea pig ZBTB11 (91% identical), rat Zbtb11 (89% identical), mouse Zbtb11 (89% identical), tropical clawed frog zbtb11 (63% identical), zebrafish zbtb11 (56% identical). Paralogues in human: PRDM15 (15% identical), ZFAT (15% identical), ZFY (13% identical), ZFX (13% identical), ZNF551 (12% identical), ZNF711 (12% identical), ZNF304 (12% identical), ZNF792 (12% identical), ZNF583 (11% identical), E4F1 (11% identical), ZNF256 (11% identical), ZNF570 (11% identical), and 26 more.
Diseases named in the same sentence as ZBTB11 in open-access papers:
ZBTB11 is named in the same sentence as 27 diseases in open-access papers, as found by Europe PMC text mining. Sharing a sentence is not in itself a finding about the gene and the disease. The quoted sentences say what the papers report.
Intellectual disability (4 papers, 2020 to 2026). "Zinc finger and BTB domain-containing protein 11 (Zbtb11) is a conserved transcription factor mutated in families with inherited intellectual disabilities and plays an important regulatory role in mitochondria." (PMID 40537021, 2026). "Recently, genome-wide target analysis showed that Zbtb11 directly regulates the expression of mitochondrial genes associated with intellectual disability." (PMID 39083515, 2024). "Zbtb11 is a conserved transcription factor mutated in families with hereditary intellectual disability." (PMID 33122634, 2020). "Recent genetic studies of consanguineous families with recessive intellectual disability (ID) identified homozygous missense mutations in human ZBTB11 as causal variants." (PMID 33122634, 2020). "ZBTB11 mutations have been identified in patients with intellectual disability and morphological brain and neuromuscular defects, although the etiology was unknown." (PMID 33122634, 2020). "Our study establishes Zbtb11 as an essential mitochondrial regulator, improves our understanding of the transcriptional mechanisms of nuclear control over mitochondria, and may help to understand the aetiology of Zbtb11-associated intellectual disability." (PMID 33122634, 2020).
bladder cancer (2 papers, 2022 to 2025). "The transcription factor ZBTB11 suppresses the proliferation and colony‐forming ability of bladder cancer cells through knockdown of its expression." (PMID 39779467, 2025). "In bladder cancer, ZBTB11 promotes the transcription of DDX1, an RNA helicase required for R‐loop clearance." (PMID 36054300, 2022). "Therefore, knockdown of ZBTB11 leads to DNA damage as a result of R‐loop accumulation, which further reduces proliferation, promotes apoptosis and increases cisplatin sensitivity of bladder cancer cells." (PMID 36054300, 2022).
COVID-19 (2 papers, 2021). A disease caused by infection with severe acute respiratory syndrome coronavirus 2. "Four genes near our chromosome 3 locus—NXPE3, ZBTB11, CEP97, and RPL24I—have been linked to COVID-19 SNPs in HGI (COVID-19 Host Genetics Initiative, 2021) and studies based on HGI data." (PMID 35222515, 2021). "Gene-based analyses identified five significant gene associations with COVID-19 positivity on chromosome 3 (p < 0.05/19,148 genes = 2.6 × 10−06): NXPE3 (p = 1.6 × 10−11), ZBTB11 (p = 5.8 × 10−11), CEP97 (p = 1.0 × 10−10), RPL24I (p = 9.4 × 10−09), and PCNP (p = 6.8 × 10−07)." (PMID 35222515, 2021).
hepatocellular carcinoma (2 papers, 2017 to 2022). A malignant tumor that arises from hepatocytes. "Lower expression in HepG2 liver cancer cells correlates with hepatocellular carcinoma expression profiling showing very low ZBTB11 expression." (PMID 28382966, 2017). "A downregulation of ZBTB11 was also reported in hepatocellular carcinoma samples." (PMID 35993275, 2022).
lung carcinoma (2 papers, 2024 to 2025). "Consistent with the notions achieved from in vitro assays, loss of Zbtb11 in a sporadic lung cancer mouse model induced by dysfunctions of the oncogene Kras and tumor suppressor gene Lkb1 demonstrated a remarkable reduction in distal metastasis of lung tumors." (PMID 38355937, 2024). "More recently, ZBTB11 was reported to participate in the long noncoding RNA (lncRNA) DUBR-mediated migration and invasion of lung cancer cells, suggesting a potential role of ZBTB11 during lung cancer progression." (PMID 38355937, 2024). "In this study, we uncovered a SET-associated transcription factor, ZBTB11, and demonstrated that ZBTB11 is a prometastatic factor in lung cancer cells in vitro and in vivo." (PMID 38355937, 2024). "Taken together, our data characterize ZBTB11 as a binding partner of the oncoprotein SET in lung cancer cells." (PMID 38355937, 2024). "Here the authors show that the transcription factor ZBTB11 drives metastasis in preclinical models of lung cancer both through SE translocation (SET)-dependent and independent manner." (PMID 38355937, 2024). "Integrated analyses of ChIP-seq and RNA-seq reveal that ZBTB11 acts as a transcription factor in lung cancer cells." (PMID 38355937, 2024). "SET cooperates with ZBTB11 in transcriptional regulation by acting as a cofactor, and the interplay between SET and ZBTB11 is critically involved in modulating the metastatic behaviors of lung cancer cells." (PMID 38355937, 2024). "Similar transcriptional regulation of these genes upon SET and/or ZBTB11 knockdown was also recapitulated in H1975 lung cancer cells." (PMID 38355937, 2024). "To investigate the functional interplay between SET and ZBTB11 in lung cancer cells, we sought to identify SET-mediated regulation of ZBTB11 direct target genes." (PMID 38355937, 2024). "Among these putative targets, 43 genes were upregulated and 76 genes were downregulated upon ZBTB11 depletion, suggesting that ZBTB11 serves as either a transcriptional activator or repressor in lung cancer cells, probably depending on the regulatory context of a given target gene." (PMID 38355937, 2024). "To investigate whether ZBTB11 serves as a transcription factor in lung cancer cells, we next performed chromatin immunoprecipitation-sequencing (ChIP-seq) to evaluate the genome-wide distribution of chromatin-bound ZBTB11." (PMID 38355937, 2024). "Taken together, our data indicate that ZBTB11 is a transcription factor in lung cancer cells." (PMID 38355937, 2024). "In addition, the reduced migration and invasion by knockdown of SET in lung cancer cells was almost completely abrogated upon concomitant ZBTB11 depletion, suggesting that ZBTB11 was one of the major TFs binding by SET to exert SET-involved metastatic regulation in the nucleus." (PMID 38355937, 2024). "However, the precise transcriptional profiles, regulatory networks, and biological consequences controlled by ZBTB11 in lung cancer remain largely unknown." (PMID 38355937, 2024). "SE translocation (SET) reportedly interacts with zinc finger and BTB domain containing 11 (ZBTB11) to promote the complex-mediated transcriptional activation of MMP9, which promotes lung cancer distal metastasis." (PMID 40665344, 2025). "Since MMP9 and PRRG2 are key downstream targets of ZBTB11 and/or SET in regulating the metastasis of lung cancer cells, we also considered them in the clinical survival analyses." (PMID 38355937, 2024). "SET interacts and collaborates with ZBTB11 to promote lung cancer cell migration and invasion, primarily through SET-ZBTB11 complex-mediated transcriptional activation of matrix metalloproteinase-9 (MMP9)." (PMID 38355937, 2024). "More importantly, this effect on cancer cell migration and invasion by SET depletion was abolished upon concomitant knockdown of ZBTB11, suggesting that SET-mediated metastatic regulation of lung cancer cells is probably dependent on the presence of ZBTB11." (PMID 38355937, 2024).
lung carcinoma (continued). "Moreover, the expression of ZBTB11 and SET in lung tissues exhibited a strong correlation, supporting the notion of cooperation between ZBTB11 and SET in promoting lung cancer progression." (PMID 38355937, 2024). "Finally, we investigated whether dysfunction of ZBTB11 and/or SET contributed to the prognosis of lung cancer." (PMID 38355937, 2024). "Similarly, our data also supported the notion that ZBTB11 maintained either positive or negative transactivity toward its target genes in lung cancer cells." (PMID 38355937, 2024).
cardiomyopathies (1 paper, 2023). "We do not see the alterations in ZBTB11 expression, nor in genes relevant to autophagy or apoptosis in our study, but this is not surprising given the divergent features of these cardiomyopathies." (PMID 37628806, 2023).
melanoma (1 paper, 2022). A malignant, usually aggressive tumor composed of atypical, neoplastic melanocytes. "Whether therapeutically targeting the ZBTB11 pathway would have a favourable outcome in NRAS mutated melanoma would require experimental evaluation." (PMID 35993275, 2022). "In addition, this study revealed an increase in Adenosine-to-Inosine editing in Alu regions and in non-repetitive regions, including the hyperediting of the MOK and DZIP3 genes in relapsed tumour samples during targeted therapy and of the ZBTB11 gene in NRAS mutated melanoma cells." (PMID 35993275, 2022). "Firstly, zinc finger and BTB domain containing 11 (ZBTB11) was identified as being hyper-edited in the NRAS mutation group, when compared to melanoma samples with BRAF or other mutations." (PMID 35993275, 2022).
metastatic tumors (1 paper, 2024). "More importantly, both ZBTB11 and SET showed a further increase in their expression in metastatic tumors, strongly supporting critical roles of aberrant ZBTB11 and SET in modulating distal metastasis of lung tumors." (PMID 38355937, 2024). "In addition, we evaluated the protein levels of ZBTB11 and SET in tissue arrays containing paired adjacent normal lung tissues and primary LUAD and distal metastatic tumors." (PMID 38355937, 2024).
microcephaly (1 paper, 2024). A congenital or acquired developmental disorder in which the circumference of the head is smaller than normal for the person's age and sex. "By contrast, the eye size in Venus-Zbtb11-expressing embryos with the reduced eye phenotype or microcephaly was significantly smaller than those in Venus-NLS-expressing embryos (0.65 to 0.70-fold decrease in average)." (PMID 39083515, 2024).
viral infection (1 paper, 2020). "The functions of SPARC/Osteonectin, Cwcv and Kazal-like Domains Proteoglycan 1 (SPOCK1), Zinc Finger and BTB Domain Containing 11 (ZBTB11), and myosin XVB (MYO15B) in viral infection are unclear." (PMID 32223537, 2020).
tumour (4 papers, 2022 to 2025). "Loss of Zbtb11 increased the collagen IV levels surrounding tumor cells." (PMID 38355937, 2024). "The primary tumor samples displayed higher expression of both ZBTB11 and SET than the adjacent tissues." (PMID 38355937, 2024). "To further investigate the role of ZBTB11 in tumor behaviors in vivo, we generated a Zbtb11 conditional knockout (cKO) mouse model by the CrispR/Cas9 technique." (PMID 38355937, 2024). "To assess the role of PRRG2 in vivo, we established a xenograft tumor model to evaluate whether PRRG2 contributes to ZBTB11-mediated regulation of tumor metastasis." (PMID 38355937, 2024). "Notably, overexpression of PRRG2 or depletion of YAP1 markedly attenuated ectopic ZBTB11-induced tumor metastasis." (PMID 38355937, 2024). "To corroborate SET-ZBTB11 complex-mediated modulation of cancer cell behaviors in vivo, we employed H1299-Luc2-tdT-2 reporter cells with stable knockdown of SET or ZBTB11 and monitored distal metastasis of the indicated cancer cells through a subcutaneous tumor xenograft mouse model." (PMID 38355937, 2024). "More importantly, knockdown of MMP9 remarkably suppressed ZBTB11-induced tumor metastasis." (PMID 38355937, 2024). "Because cisplatin‐based chemotherapy mainly induces double‐strand breaks and apoptosis in tumour cells, suppressing the ZBTB11/DDX1 signalling axis may increase the cisplatin sensitivity of BC cells." (PMID 36054300, 2022). "Collectively, these data suggest that SET cooperates with ZBTB11 in transcriptional regulation and prompted us to focus on the potential roles of the SET-ZBTB11 protein complex in the regulation of extracellular matrix-related biological processes upon tumor initiation and progression." (PMID 38355937, 2024). "Notably, despite no statistical significance, loss of Zbtb11 still showed a tendency of reduced or slowed formation of the primary lung tumors induced by aberrant Kras and Lkb1, supporting ZBTB11 as an oncoprotein that may contribute to tumor initiation, to some extent, in vivo." (PMID 38355937, 2024). "In addition, depletion of SET and/or ZBTB11 did not impair primary tumor growth." (PMID 38355937, 2024). "Taken together, our data indicate PRRG2 as a direct target of ZBTB11, which contributes to ZBTB11-, but not SET-, mediated regulation of tumor metastasis." (PMID 38355937, 2024).
cancer (3 papers, 2021 to 2024). A tumor composed of atypical neoplastic, often pleomorphic cells that invade other tissues. "Using the ENCODE database, we subsequently found binding peaks of ZBTB11 in the promoter regions of DDX1 in human cancer K562 and MCF‐7 cells." (PMID 36054300, 2022). "Overexpression of the YAP1-S127A mutant readily reversed the suppressive effect on cancer cell migration induced by PRRG2 overexpression or ZBTB11 knockdown." (PMID 38355937, 2024). "Taken together, although the characterization of ZBTB11 in cancer biology is just emerging and far from complete, our current study sheds light on a critical role of ZBTB11 as a prometastatic regulator." (PMID 38355937, 2024). "By mining The Cancer Genome Atlas data, we found that the mRNA levels of ZBTB11 and DDX1 were positively correlated in BC tissues." (PMID 36054300, 2022). "Therefore, our study highlights ZBTB11 as an oncogene whose dysfunction plays a profound role in promoting cancer cell metastasis through multiple mechanisms." (PMID 38355937, 2024). "Interestingly, complete abrogation of Zbtb11 also showed a tendency to limit primary lung tumor growth, reflecting the mechanistic diversity and complexity of ZBTB11 in regulating cancer cell metastasis in vivo." (PMID 38355937, 2024). "Moreover, both the repression of Mmp9 and the activation of Prrg2 were easily recapitulated in Zbtb11 KO MEFs, further confirming our previous results in cancer cells where MMP9 and PRRG2 are critical downstream targets of ZBTB11." (PMID 38355937, 2024). "The molecular implications of ZBTB11 in cancer cells are poorly reported." (PMID 38355937, 2024). "SET and ZBTB11 jointly promoted cancer cell metastasis, but the mechanisms could be diversified." (PMID 38355937, 2024). "In this study, we could not obtain a complete ZBTB11 knockout cancer cell line, although clones with one allele disruption were always successfully maintained after CrispR/Cas9-mediated gene editing." (PMID 38355937, 2024). "In addition, the genes coregulated by ZBTB11 and SET, such as MMP9 and SPARC, have been well validated to participate in the regulation of cancer cell migration and invasion." (PMID 38355937, 2024). "Moreover, we successfully detected the interaction between endogenous SET and ZBTB11 in H1299 cells, indicating that the SET-ZBTB11 protein complex can form under physiological conditions in cancer cells." (PMID 38355937, 2024). "To validate the regulatory role of the SET-ZBTB11 complex under more physiological conditions, we disrupted the SET-ZBTB11 interaction by interfering with endogenous SET and/or ZBTB11 to evaluate potential alterations in cancer cell behaviors in H1299 cells." (PMID 38355937, 2024). "Since knockdown of ZBTB11 displayed a more robust effect on cancer cell migration and invasion than SET depletion, we speculated that ZBTB11 likely maintains additional ways to modulate metastasis independent of SET-ZBTB11 complex formation." (PMID 38355937, 2024). "Rs4801778-T (PLEKHA4), rs11919389-C (ZBTB11), rs13050728-C (IFNAR2), and rs10774671-A (OAS1) exhibited a positive or negative regulation in TULP2, HSD17B14, LOC285359, LOC100009676, SENP7, IFNAR2, OAS3, and OAS1 in multiple cancer types." (PMID 35082790, 2021). "Re-expression of SET-FL, but not SET-ΔAD, which does not bind with ZBTB11, obviously elevated cell migration and invasion, suggesting that the interaction between SET and ZBTB11 is critical for SET/ZBTB11-mediated metastatic regulation of cancer cells." (PMID 38355937, 2024). "Indeed, although overexpression of both ZBTB11 and SET displayed a promotive effect on cancer cell migration and invasion, only full-length SET, but not acidic domain-truncated SET that failed to bind with ZBTB11, enhanced ZBTB11-dependent metastatic regulation." (PMID 38355937, 2024).
mitochondrial disease (1 paper, 2020). "We therefore propose that at least some of the phenotypical features reported in patients with ZBTB11 mutations are manifestations of a mitochondrial disease." (PMID 33122634, 2020).
neurodevelopmental disorder (1 paper, 2024). A behavioral and cognitive disorder with onset during the developmental period that involves impaired or aberrant development of intellectual, motor, or social functions. "In summary, our study provides new insights into the molecular mechanisms of anterior patterning of the neuroectoderm by cooperation with Zbtb11 and phosphorylated form of Otx2 as well as the neurodevelopmental disorders caused by dysregulation of Zbtb11." (PMID 39083515, 2024). "Our study showing the interactions between Zbtb11 and Otx2 might provide a basis for the therapeutic potential of Zbtb11 in neurodevelopmental disorders associated with mitochondrial dysfunction, as well as for elucidating the molecular mechanisms of early anterior neural development." (PMID 39083515, 2024).
ZBTB11 also shares sentences with these, for which no sentence is quoted: Ataxia (1 paper); Bardet-Biedl syndrome (1); Cerebellar atrophy (1); cone-rod dystrophy (1); developmental and epileptic encephalopathy (1); Down syndrome (1); granulocytopenia (1); Leigh syndrome (1); liver cancer (1); macular dystrophy, vitelliform (1); promyelocytic leukaemia (1); respiratory failure (1); retinitis pigmentosa (1).